EPHB4 (EPH receptor B4)
Diseases named in the same sentence as EPHB4 in open-access papers (continued):
Sharing a sentence is not in itself a finding about the gene and the disease.
cerebrovascular disorder (1 paper, 2025). A disorder resulting from inadequate blood flow in the vessels that supply the brain. "A VUS was found in one patient (3%) in the EPHB4 gene, whereas variants in novel genes possibly associated with cerebrovascular disorders were reported in five out of the 29 individuals (17%)." (PMID 40259928, 2025).
cervical cancer (1 paper, 2021). A primary or metastatic malignant neoplasm involving the cervix. "Likewise, EPHB4 and ephrin-B2 expression were reported higher in cervical cancer and Cervical Intraepithelial Neoplasia specimens and associated with tumor diameter, with EPHB4 additionally associated with disease stage." (PMID 34445116, 2021).
childhood cancers (1 paper, 2025). "Our CAR-T therapy targeting five common membrane protein cancer antigens—EphB4, CLDN1, LAT1, ROBO1, and GPC3—may be effective against many solid tumors, including childhood cancers." (PMID 40076777, 2025).
choroidal neovascularization (1 paper, 2013). An eye disorder described by the growth of new blood vessels that originate from the choroid through a break in the Bruch membrane into the sub–retinal pigment epithelium (sub-RPE) or subretinal space. "The aim of this study was to determine the effect of the EphB4 monoclonal antibody on experimental choroidal neovascularization (CNV) progression." (PMID 23596494, 2013).
chronic myeloid leukemia (1 paper, 2022). "The oncogenic role of ephrin type‐B receptor 4 (EPHB4) has been reported in many types of tumors, including chronic myeloid leukemia (CML)." (PMID 35689424, 2022).
CM-AVM syndrome (1 paper, 2025). "Our systematic review highlights distinct cerebrovascular phenotypes associated with RASA1 versus EPHB4 mutations in CM-AVM syndrome." (PMID 41398316, 2025).
cocaine abuse (1 paper, 2007). Disorders related or resulting from use of cocaine. "Since MMPs can degrade the entire extracellular matrix, coordinated regulation of RECK, MMP9, CTGF and EphB4 suggests expansion of the extracellular matrix occurs with morphological remodeling of the hippocampus in response to chronic cocaine abuse." (PMID 18000554, 2007).
cognitive decline (1 paper, 2025). "Finally at the observed protein levels, higher EPHB4 levels were associated with hippocampal atrophy - a key indicator of neuroinflammation and cognitive decline." (PMID 40799764, 2025).
colitis (1 paper, 2019). Inflammation of the colon. "EphB4 protein 20 μg/kg elicited protective effects against colitis: a marked reduction of DAI and of colonic macroscopic damage, thickness, and shortening occurred." (PMID 31297055, 2019).
coronary artery aneurysm (1 paper, 2023). "However, little is known about EphrinB2/EphB4 in the pathogenesis of Kawasaki disease (KD) and coronary artery aneurysm formation." (PMID 37111257, 2023). "Our findings suggest a close relationship between EphB4 downregulation and endothelial cell lesions, and EphB4 may represent a new marker for the clinical prediction of coronary artery aneurysms in KD patients." (PMID 37111257, 2023).
Crohn disease (1 paper, 2021). A gastrointestinal disorder characterized by chronic inflammation involving all layers of the intestinal wall, noncaseating granulomas affecting the intestinal wall and regional lymph nodes, and transmural fibrosis. "Recently, we showed that EphA/ephrin-A proteins can modulate the acute inflammatory responses induced by mesenteric ischemia/reperfusion, while beneficial effects were granted by EphB4, acting as EphB/ephrin-B antagonist, in a murine model of Crohn’s disease (CD)." (PMID 34074058, 2021).
dilated cardiomyopathy (1 paper, 2019). Cardiomyopathy which is characterized by dilation and contractile dysfunction of the left and right ventricles. "We propose that EphB4 maintains critical functional properties of the adult cardiac vasculature and thereby prevents dilated cardiomyopathy-like defects." (PMID 31782728, 2019). "In line with the close proximity of capillaries and cardiomyocytes, EC-specific inactivation of the Ephb4 gene induces a hypertrophic response in the latter, which triggers heart remodeling and gives rise to a phenotype that resembles human dilated cardiomyopathy in its features and development." (PMID 31782728, 2019).
Erythema (1 paper, 2020). Redness of the skin, caused by hyperemia of the capillaries in the lower layers of the skin. "Herein, we report one male patient with facial erythema who was initially thought to have PWSs because of the unilateral and segmental distribution of his red facial lesions but was later diagnosed with CM-AVM2 syndrome based on a germline EPHB4 mutation." (PMID 32635943, 2020).
Hydrocephalus (1 paper, 2025). Hydrocephalus is an active distension of the ventricular system of the brain resulting from inadequate passage of CSF from its point of production within the cerebral ventricles to its point of absorption into the systemic circulation. "The prominence of neonatal vGaM in EPHB4-mutated cases means CM-AVM2 often presents early, even prenatally or in the neonatal period, with high-output cardiac failure or hydrocephalus, necessitating urgent intervention." (PMID 41398316, 2025).
insulinomas (1 paper, 2010). "Furthermore, the simultaneous suppression of Dll4/Notch and Ephrin-B2/EphB4 signaling in sEphB4-Alb treated RT2 Dll4+/- mice drastically reduced the vessel diameters and their mural cell coverage, even though the total PECAM-positive area apparently similar to PBS-treated Dll4+/+ insulinomas." (PMID 21092311, 2010).
intestinal tumor (1 paper, 2012). "EphB4+/− mice: enhanced tumor growth in an intestinal tumor genesis model." (PMID 24213317, 2012).
metastasis (1 paper, 2021). The spread or migration of cancer cells from one part of the body (where they first appeared) to another. "EPHB4 expression was not significantly related to the age or sex of OSCC patients (p>0.05), but was positively correlated with lymph metastasis, clinical stage and differentiation (p<0.05)." (PMID 34539874, 2021).
myelogenous leukemia (1 paper, 2022). "EPHB4 knockdown inhibited growth of K562 cells (a human immortalized myelogenous leukemia cell line)." (PMID 35689424, 2022).
pancreatic ductal adenocarcinoma (1 paper, 2021). An infiltrating adenocarcinoma that arises from the epithelial cells of the pancreas. "We validated EphB4 overexpression using pancreatic ductal adenocarcinoma tissue microarrays (TMAs) using immunohistochemistry (IHC)." (PMID 34298619, 2021). "We identified ephrin type-B receptor 4 (EphB4) as hyperactivated in PDXs derived from pancreatic ductal adenocarcinoma." (PMID 34298619, 2021). "In summary, we present a comprehensive landscape of tyrosine phosphoproteome with EphB4 as a promising therapeutic target in pancreatic ductal adenocarcinoma." (PMID 34298619, 2021). "Overall, our results show that EphB4 could serve as a therapeutic target in the treatment of pancreatic ductal adenocarcinoma." (PMID 34298619, 2021).
peritoneal disease (1 paper, 2007). "Our human tumour data confirm that increased expression of EphB4 correlates with the presence of peritoneal disease and ascites, consistent with extra-ovarian spread of the disease." (PMID 17353927, 2007).
pleural mesothelioma (1 paper, 2015). A neoplasm that arises from the mesothelial cells of the pleura. "Of note, no non-synonymous EPHB4 mutations were detected in HNSCC or pleural mesothelioma tissues." (PMID 26073592, 2015).
preeclampsia (1 paper, 2009). Preeclampsia is a hypertensive disorder of pregnancy that is characterized by new-onset hypertension with proteinuria presenting after 20 weeks of gestation, and depending on mild or severe forms may initially present with severe headache, visual disturbances, and hyperreflexia. "Although the clinical status of the placentas did not appear to be related to the methylation pattern of EPHB4 and WNT2 in human, a phenotypic effect of these MAP genes on the human placenta cannot be excluded as only two clinical features, IUGR and preeclampsia were evaluated." (PMID 19838307, 2009).
RASopathy (1 paper, 2023). Developmental syndromes caused by germline mutations (or in rare cases by somatic mosaicism) in genes that alter the Ras subfamily and mitogen-activated protein kinases that control signal transduction. "We describe novel variants in several LA genes, including a likely pathogenic variant in PIEZO1, and VOUS in PIEZO1, ITGA9, CELSR1, EPHB4, and TIE1, as well as novel VOUS in RASopathy genes." (PMID 36959127, 2023).
retinal diseases (1 paper, 2021). "EphrinA1, ephrinA4, ephrinA5, EphA2, EphA7, ephrinB2, EphB3, and EphB4 seem to be the most important in the context of retinal diseases." (PMID 34201393, 2021).
Sepsis (1 paper, 2019). Sepsis is defined as life-threatening organ dysfunction caused by a dysregulated host response to infection. "Previous research has described an increased expression of synaptic genes during the progression from normal aging to neurodegenerative disease, including genes we observed to increase in older males on day 4 of sepsis (Cacnb1, Cacna1a, Ephb4, Glul, Jph3, Mink1, Nrxn2, Grasp)." (PMID 31278440, 2019).
uveitis (1 paper, 2026). An inflammatory process affecting a part of or the entire uvea. "Ang-1, Ang-2, Tie-2, EphrinB2, EphB4, and endocan regulate vascular stability, retinal neovascularization, and inflammation, potentially contributing to BD-associated uveitis." (PMID 42071810, 2026). "This cross-sectional study investigates the role of angiopoietins, EphrinB2/EphB4 signaling, and endocan in the development of active uveitis in BD patients." (PMID 42071810, 2026). "In the group with active uveitis, EphB4 (r = -0.774), Ang-2 (r = -0.763), and Tie-2 (r = -0.701) were negatively and highly significantly correlated with best corrected visual acuity (P < .001)." (PMID 42071810, 2026).
venous insufficiency (1 paper, 2021). Impaired venous blood flow or venous return (venous stasis), usually caused by inadequate venous valves. "A primary lymphatic anomaly, caused by mutations in the receptor tyrosine kinase EPHB4, was recently described, with these patients also presenting with venous insufficiency." (PMID 34403370, 2021). "In addition to an increased risk of lymphatic-related fetal hydrops, we show that patients carrying heterozygous mutations in EPHB4 had very few VVs, with early onset deep venous reflux indicating that the observed venous insufficiency was due to VV aplasia." (PMID 34403370, 2021).
tumor (160 papers, 2005 to 2026). "EphB4 is thus required for initiation of the tumor in the context of PTEN deficiency, either through cell autonomous signaling or through simultaneous induction of its high affinity cell membrane bound ephrin-B2." (PMID 40044981, 2025). "Our data show that loss of cancer cell EphB4 results in a combination of immunosuppression and intrinsic changes in tumor cell behavior, thereby allowing for proliferation of the primary tumor and dissemmination of cancer cells to distant sites." (PMID 39489818, 2025). "c-Myc levels were markedly reduced in sEphB4-alb treated mice and loss of c-Myc was also confirmed in PC tumor cell lines following EphB4 knockdown." (PMID 40044981, 2025). "Further, the loss of a singular allele of EphB4 in a genetic model of intestinal cancer with adenomatous polyposis coli (Apc) mutation resulted in greater epithelial proliferation and bigger tumours in the small intestine." (PMID 36830852, 2023). "Studies on cell proliferation and metastasis have revealed that the erythropoietin-producing human hepatocellular B4 (EPHB4) is an important regulator of tumor functions in OSCC, associated with lymph node metastasis, differentiation, and poor prognosis." (PMID 37511951, 2023). "The targeting of EPHA2, EPHA10, EPHB4, ephrin-A2, ephrin-A4, as well as ephrin-B2 in BC cells or xenograft models is associated with apoptosis induction, tumor regression, anticancer immune response activation, and impaired cell motility." (PMID 36499598, 2022). "The membrane-bound ephrin-B2 ligand and its receptor EPHB4 are expressed in tumor-specific blood vessels and appear to play roles in tumor-associated angiogenesis." (PMID 35694408, 2022). "EPHB4 overexpression was linked to low tumor differentiation, high Ki67 index, and presence of LN metastasis in a series of 93 lung adenocarcinoma tissues." (PMID 34445116, 2021). "Current studies have suggested that the mechanism by which EPHB4 plays a role in promoting or suppressing cancer remains elusive and is closely linked to its context in various types of tumours." (PMID 34539874, 2021). "We have developed piggyBac transposon (PB)‐mediated CAR‐T cells redirected towards the Ephrin type‐B receptor 4 (EPHB4), which is a tumor‐associated antigen expressed not only on various tumors but also on certain normal tissues at low to moderate levels." (PMID 34123382, 2021). "Another study linked EPHB4 and ephrin-B2 overexpression to higher tumor stage, LN metastasis, higher tumor size and poorer prognoses." (PMID 34445116, 2021). "Signaling through EphrinB2 and EphB4 has been directly associated with tumor angiogenesis and with tumor resistance to anti-angiogenic therapy." (PMID 33614496, 2020). "In fact, APC min mice with a single allele inactivation of EphB4 showed shorter lifespan, larger tumor size in the small intestine and more abundant tumors in the large intestine." (PMID 32316101, 2020). "The dual function of EphB4 as tumor promoter or suppressor associated with its EFNB2 ligand opens a therapeutic window for modulating EphB4 activity in tumor cells." (PMID 31949258, 2020). "EPHB4 has been associated with tumour angiogenesis, growth and metastasis, thus making it a valuable and attractive target for drug design for therapeutic applications." (PMID 32336043, 2020). "EphB4-ephrinB2 signalling was also associated with increased tumor angiogenesis and tumor progression as well as with resistance to anti-angiogenic therapy." (PMID 31690961, 2020). "The changes in tumor cell metabolism after EPHB4 inhibition were associated with MYC downregulation, likely mediated by the SRC/p38 MAPK/4EBP1 signaling cascade, known to impair cap-dependent translation." (PMID 31641103, 2019). "EphB4 has been associated with tumor growth, tumor suppression, and apoptosis in multiple types of cancers." (PMID 28817624, 2017).
tumor (continued). "Other members of the Eph receptor and ephrin families, including EphA2, EphB4, ephrin A1, and ephrin A3, have previously been implicated in radioresistance in different tumor models." (PMID 25879388, 2015). "Overexpression of EphB4 correlates with advanced tumour stage and is associated with poor clinical outcome." (PMID 17353927, 2007). "In order to elucidate the underlying mechanism by which EphB4 shRNA influences Treg function, Tregs isolated from the spleen and lymph nodes of tumor-bearing mice (MOC2 control shRNA or EphB4 shRNA) were sorted and subjected to mass spectrometry proteomics analysis." (PMID 39489818, 2025). "An example is EphB4, which has been linked to tumor angiogenesis, growth, and metastasis." (PMID 39457707, 2024). "Inhibition of EphB4/ephrinB2, in vitro and in a mouse xenograft model, was associated with an improvement of antitumor responses, particularly when combined with radiotherapy (RT), which resulted in notable reductions in tumor growth in cases of PDAC." (PMID 39839790, 2024). "Indeed, EphB4 has been described as a tumor promoter associated with proliferation, invasion, and angiogenesis." (PMID 38651144, 2024). "In parallel, the EPHB4/ephrin-B2 targeting could suppress the pro-tumorigenic immune infiltrates, causing further tumor regression." (PMID 36769332, 2023). "Furthermore, targeting of EPHA10, EPHB4, ephrin-A2, and ephrin-A4, as well as ephrin-B2 in BC cells or xenograft models was associated with tumor regression, anticancer T-cell activation, and impaired cell motility." (PMID 36499598, 2022). "Interestingly, this was a common trend observed in all the other tumor models (Ly2, MEER, and CUHN013) analyzed in our study suggesting a tumor cell-intrinsic increase in cell growth due to the loss of EphB4 on cancer cell." (PMID 35725568, 2022). "Indeed, we did not observe any signs of adverse effects including weight loss, suggesting that off-tumor toxicity induced by murine EPHB4/human EPHB4-CAR-T cell interaction was negligible." (PMID 33816783, 2021). "In summary, loss of PDCD10 activates GBM cells and promotes tumor growth via triggering EphB4." (PMID 32850441, 2020). "However, EphB4 has been also associated with a paradoxical tumor-suppressing effect in an immortalized non fully malignant cancer cell (MCF-10A)." (PMID 31270394, 2019). "As a member of receptor tyrosine kinases, EphB4 is frequently implicated in tumor pathogenesis." (PMID 27827952, 2016). "Furthermore, two of the amino acids targeted by mutations to define the EphA3 interface, V231D and N232I, are within the 8 amino acid sequence that is defined as the epitope through which the EphB4 H200 antibody acts to cause tumour cell death." (PMID 25831049, 2015). "Thus, accumulating evidence suggests that loss of EphB2 expression, in concert with a gain of EphB4 expression, is a common pathway towards switch from normal to tumor development and progression." (PMID 25148033, 2014). "Ephrin type-B receptor 4 (EphB4) belongs to the Ephrin-B receptor family of receptor tyrosine kinases, which are involved in cell adhesion, migration, and angiogenesis, and EphB4 overexpression is closely associated with tumor invasion, metastasis, and prognosis." (PMID 39949739, 2025). "However, when EphB4 knock out tumors in mice were treated with EphA4 inhibitor, a significant tumor growth reduction was observed, suggesting that EphA4 plays a compensatory role to enhance tumor growth in vivo following the loss of cancer cell EphB4." (PMID 35725568, 2022). "In a study that enrolled 46 papillary and 10 follicular thyroid carcinoma tissues, as well as 71 benign thyroid samples, EPHB4 expression was found to be higher in malignant specimens compared with their benign counterparts, while its overexpression was associated with larger tumor sizes." (PMID 34445116, 2021).